IGF1 (insulin like growth factor 1)
Diseases named in the same sentence as IGF1 in open-access papers (continued):
Sharing a sentence is not in itself a finding about the gene and the disease.
cancer (continued). "Nevertheless, the association between IGF1 and cancer growth has raised several concerns, while several other mediators have been identified as key mediators of the cachexia process (i.e., Atrogin1 (MAFbx) and MuRF1 (Trim63))." (PMID 38334644, 2024). "Metformin improves metabolic health and decreases circulating insulin and insulin-like growth factor 1 (IGF-1), both of which are known to promote cancer risk and progression." (PMID 38543182, 2024). "IGF-1 is a growth hormone associated with cancer promotion, contributing to the genesis and progression of malignant tumors." (PMID 38535034, 2024). "IGF1, a member of the insulin superfamily, is an important regulator of tissue growth and development and is linked to the development of numerous cancers." (PMID 38221934, 2024). "Encouraging pre-clinical observations with novel IGF-1R antagonists and epidemiological surveys linking IGF-1 levels to cancer risk, led to many clinical trials with biologicals and small molecules, but with sobering results." (PMID 39638246, 2024). "Although beneficial for growth/repair and regulation of muscle hypertrophy, high levels of IGF-1 are associated with increased cancer risk." (PMID 40443827, 2024). "Investigators found that the regimen reduced levels of insulin-like growth factor 1 (IGF-1), a hormone associated with several types of cancer, following three FMD cycles within a 3-month period." (PMID 38276554, 2024). "The involvement of insulin and its receptor in cancer development is underscored by the fact that elevated insulin levels can augment IGF-1 production, a factor linked to an increased risk of specific cancers." (PMID 39301314, 2024). "A restricted diet is strongly linked to slowing cancer progression through mechanisms involving the IGF-1 pathway and mTOR activation." (PMID 39596005, 2024). "Elevated levels of insulin and insulin-like growth factor-1 (IGF-1) associated with T2DM have mitogenic effects on cancer cells, promoting proliferation and inhibiting apoptosis 43,44." (PMID 39020091, 2024). "High insulin levels caused by fructose-induced insulin resistance also raise IGF-1 levels, which foster cancer cell proliferation while suppressing apoptosis." (PMID 39310400, 2024). "IGF1 is associated with an increased risk of colorectal, prostate, breast, and lung cancers, while IGF2 is implicated in colorectal cancer, liver cancer, and prostate cancer." (PMID 38339282, 2024). "EGCG has been shown in preclinical studies to demonstrate anti-cancer activity through a variety of mechanisms, including decreases in IGF1, tumor-associated oxidative stress and angiogenesis, and androgen receptor antagonism." (PMID 39840030, 2024). "This last concept has been supported by an epidemiological study conducted on a cohort of congenital IGF1 deficient patients, which revealed a marked reduction in cancer incidence in homozygous patients compared to their heterozygous relatives." (PMID 37941907, 2023). "While a link between high IGF1 levels and enhanced cancer risk has been recognized more than twenty-five years ago, a potential protective role of low IGF1 dosages has been more difficult to demonstrate." (PMID 37941907, 2023). "Disruption of the insulin/IGF-1 signaling pathway is associated with several diseases (cardiovascular and neurodegenerative diseases, type II, cancer) and aging." (PMID 37895144, 2023). "Insulin growth factor 1 (IGF1), Insulin growth factor (IGF2), IGF receptor (IGFR) and IGF Binding Proteins (IGFBPs) are all members of the IGF signaling family and have been implicated in cancer." (PMID 37029430, 2023). "IGF-1 levels have been reported to be associated with an increased risk of cancer; thus, we performed autopsies and collected all major organs for histopathological analysis." (PMID 36602878, 2023).
cancer (continued). "Based on previous findings, we will focus on the correlation of IGF-1 signaling with the risk of PCa, propensity for metastasis, therapy resistance, and cancer-related death in this review." (PMID 36831629, 2023). "The presence of high levels of IGF-1 in the circulation for a long time was stated to cause many carcinogenic stages to progress and develop cancer due to the fact that IGF-1 has mitogenic and antiapoptic effects." (PMID 37763806, 2023). "in a meta-analysis study declared that IGF1 rs35767C>T polymorphism hadn’t a significant association with cancer risk." (PMID 37284192, 2023). "IF can reduce cancer risk and DNA damage by increasing the levels of insulin-like growth factor inhibitory protein and ketone bodies as well as reducing IGF-1, insulin, and glucose concentrations." (PMID 36911497, 2023). "Although IGF-1 can stimulate neurogenesis and promote cognition in short-term, some studies have demonstrated that chronic administration of IGF-1 causes side effects such as accelerated aging, cancer development, and decreased lifespan." (PMID 36691085, 2023). "NRP1 was closely associated with a variety of genes in pan-cancer studies, such as IGF-1, PDIA3, and CD36." (PMID 37450415, 2023). "IGF-1 levels are positively correlated with carcinogenic risks, and deficiency of the growth hormone receptor also leads to IGF-1 deficiency, which reduces the risk of cancer and DNA damage." (PMID 36911497, 2023). "Previous studies evaluated the association of IGF1 rs35767C>T with the risk of different cancers which revealed contradicting results." (PMID 37284192, 2023). "In particular, the T cell activation genes Rac2 and Igf1 were increased while the malignant tumor-associated genes Mgl2, Tnfrsf9, Vegfa as well as the M2 macrophage markers Retnla and Arg-1 were decreased." (PMID 37925462, 2023). "This link is attributed in part to the increased utilization of glucose by cancer cells, and increase in the circulating levels of insulin-like growth factor-1 (IGF-1), which is also associated with increased risk of cancers." (PMID 35917304, 2022). "In particular, biological pathways such as insulin-like growth factor-1 (IGF-1) signaling are involved in both adult body height and carcinogenesis and therefore considered a possible causal link regarding height and cancer risk." (PMID 36085535, 2022). "Elevated endocrine IGF1 has been consistently associated with an enhanced cancer risk, whereas IGF1 levels are reduced during aging." (PMID 36291127, 2022). "IGF-1 has been associated with the development and progression of some cancer types due to its function in activating the MAPK and PI3K signaling pathways." (PMID 35370981, 2022). "In animals with significantly reduced IGF-1 concentrations caused by genetically-determined deficiencies, the incidence of other diseases, such as cancer and kidney disease, were also significantly lower." (PMID 35832183, 2022). "Epidemiological studies have identified an association between height, IGF-1, oestradiol, and cancer incidence to provide clues to cancer aetiology." (PMID 35729236, 2022). "Metabolic alterations were previously found to correlate with both IR and cancer through dietary risk factors (e.g. hypercaloric diet, low fibers etc.)that induces inflammation and oxidative stress, or promote IGF-1 secretion that acts as a strong mitogen." (PMID 35921366, 2022). "In dwarf, long-lived mice short of the growth hormone receptor had low IGF-1 levels, were insulin-sensitive, and had a reduced risk of cancer and diabetes despite their obesity." (PMID 35534591, 2022). "Studies illustrated that carbohydrate intake is positively associated with cancer via insulin and the related hormone, IGF-1." (PMID 35672814, 2022). "A tight control of IGF bioavailability is necessary, as, for instance, increased serum levels of liver-produced IGF1 correlates with higher risk of developing BC and other cancers." (PMID 36093095, 2022).
cancer (continued). "In population-based studies, the research on IGF-1 gene polymorphism has focused on longevity, cancers, and common chronic diseases." (PMID 35498133, 2022). "For example, the overexpression of IGF-1 in breast cancer cells in vitro was associated with poor prognosis of clinical cancers and correlated with the sensitivity to BMS-754807 in patients with triple-negative breast cancer in vivo." (PMID 36233084, 2022). "The risk of IGF-1 in cancer is further established in deciphering the mechanism of height to cause cancer." (PMID 35729236, 2022). "Insulin increases the secretion of growth-promoting substances such as IGF-1 (insulin like growth factor-1) causes higher growth of tumor and cancer cells, thus increasing the risk of cancer." (PMID 35685489, 2022). "This elevates the levels of free IGF-1 released from the liver, which are associated with cell growth and proliferation and can harm cancer patients." (PMID 35745105, 2022). "This is consistent with its capacity to inhibit pathways linked to cancer, including Wnt, IGF-1, TGF-β and NF-κB." (PMID 35903083, 2022). "Increased levels of IGF-1 were associated with several common cancer types because IGF-1 has mitogenic and antiapoptotic effects." (PMID 36079756, 2022). "Consistent with its potent antiapoptotic and prosurvival actions, elevated systemic levels of IGF1 seem to confer an enhanced cancer risk." (PMID 34204736, 2021). "The epidemiological observation that patients with LS, the best characterized entity under the spectrum of the congenital IGF1 deficiencies, are protected from cancer development is of major clinical relevance." (PMID 34204736, 2021). "While high endocrine IGF1 is linked to increased cancer risk, epidemiological studies have shown that LS patients are protected from cancer development." (PMID 34204736, 2021). "CSCs are associated with chemoresistance, and in mouse models, cancer treatment with chemotherapy upregulated IGF1 expression in tumor ECs, which activated IGF1 receptors on cancer cells, making them resistant to chemotherapy." (PMID 34073394, 2021). "In cachectic rodents and patients, the expression of IGF-1 in muscles and in the circulation decreases In one study, IGF-1 administration has been shown to reduce weight loss and improve survival in cancer-bearing rodents." (PMID 33401549, 2021). "In humans, both low and high levels of IGF-1 have been associated with increased mortality from cancer and cardiovascular disease." (PMID 33587031, 2021). "IGF1 has been implicated in promoting mitogenic and metastatic cancer cells, which enhances CC invasiveness and proliferation." (PMID 34551673, 2021). "The risk of cancer increases in diabetic patient as target tissues of ovarian steroid hormones have higher concentration of IGF-1 and increased expression of IGF1R, IRS-1 and IRS-2." (PMID 34535145, 2021). "Epidemiological and clinical studies provide evidence that high endocrine IGF1 correlates with increased cancer risk." (PMID 34220714, 2021). "Reduced inflammation, increased insulin sensitivity, and protection against cancer are shared between humans and mice with GH/IGF1 deficiency." (PMID 34118183, 2021). "Nevertheless, it has been shown that IGF-1 receptor (IGF-1R) is overexpressed in CRC and it is well established that the association of IGF-1 with its receptor stimulates cell proliferation and survival thus contributing to cancer development." (PMID 34830295, 2021). "IGF1 is involved in a number of carcinogenesis-related processes, including cell proliferation and apoptosis leading to an increased risk of cancers." (PMID 34858769, 2021). "Perhaps most interestingly, a few studies have also reported a more complex U‐shaped relationship between IGF‐1 and all‐cause, cardiovascular, and cancer mortality, in which individuals with the highest and lowest levels of IGF‐1 tend to have worse outcomes." (PMID 34363732, 2021).
cancer (continued). "While high circulating IGF1 is regarded as a risk factor in cancer, epidemiological studies have shown that LS patients are protected from cancer development." (PMID 34204736, 2021). "Increased insulin and IGF1 levels have been shown to correlate with an increased risk of several cancer types." (PMID 34191793, 2021). "Population studies provide substantial direct and circumstantial evidence that cancer risk and cancer prognosis are influenced by IGF-1 and insulin levels." (PMID 34804946, 2021). "Above normal levels of circulating IGF-1 are associated with an elevated risk of developing several primary cancer types including colorectal and breast." (PMID 34572888, 2021). "The rationale for this quest was the fact that elevated IGF1, as alluded to above, is regarded as a risk factor for cancer." (PMID 34769292, 2021). "Patients affected by Laron syndrome, which is characterized by a congenital IGF1 deficiency due to mutation or deletion of the growth hormone releasing hormone (GH-R) gene, are protected from cancer development." (PMID 34440844, 2021). "These mutations include focal amplification of IGF1R and IGF1, and frameshift indels in the recessive cancer genes IGF2R and IGFBP5." (PMID 33673232, 2021). "Preliminary research indicated a substantial genetic contribution to variations in IGF and IGFBP levels in adults, and attempts were made to identify genetic variants associated with IGF-1 levels and their possible predictive value in various types of cancer." (PMID 34959885, 2021). "A remarkable exception to this pattern is the case of cancer, which is typically associated with a positive correlation with IGF1 levels." (PMID 34769292, 2021). "Consistent with our results, IGF-1/IGF-1R signaling was reported to be associated with Hif-1α or Hif-2α expression in cancers and in cells of somatic lineage." (PMID 34381769, 2021). "Not surprisingly, both elevated concentrations of insulin and IGF-1 are associated with multiple cancer types, including breast, endometrium, pancreas and colon." (PMID 34572814, 2021). "There are several clinical studies and animal studies showing that high IGF-1 and GH levels are associated with cancer development and progression." (PMID 33389987, 2021). "IGF-1 has also been implicated in increased cancer risk of breast, colorectal, lung, and other cancers." (PMID 34695806, 2021). "Perturbation of the IGF-1 signaling pathway has been associated with a diverse set of diseases, including muscle, cardiovascular, metabolic, neurodegenerative and cancer." (PMID 33466349, 2021). "In genetically modified knock‐down and knock‐out models, attenuated growth hormone (GH)/IGF‐1 signaling generally improves the health of mice, delaying age‐associated pathologies such as sarcopenia, immunosenescence, and cancer." (PMID 34363732, 2021). "Active physical activity can not only reduce the risk of cancer by reducing weight but also reduce the cancer risk by reducing the level of insulin, IGF-1, IGF-binding protein 3 and leptin in the body." (PMID 35083251, 2021). "Previously, we reported that the phosphorylation of PKM2 at Ser-202 by AKT promotes the growth of cancers associated with aberrant IGF-1 signaling." (PMID 34359752, 2021). "Several clinical studies in this context have found an association between IGF-1 and IGF-1:IGFBP3 ratio with the development of cancer." (PMID 34681797, 2021). "One noteworthy finding of this study was the significant association patterns of the 21-gene RS and the individual cancer-related genes with specific metabolic factors and biomarkers of insulin and the IGF1 axis." (PMID 34456877, 2021). "The conditional F-statistic for the multivariable analysis of the association of BMR and IGF1 with cancer and neoplasm was 39 for BMR and 40 for IGF1." (PMID 34567085, 2021). "Epidemiologic evidences indicated that high serum levels of IGF1 correlate with increased risk of cancer." (PMID 33673232, 2021).
cancer (continued). "Mounting evidence has additionally shown that cancer prognosis is affected by insulin and IGF-1 circulating levels, independently of cancer risk." (PMID 32351453, 2020). "In conclusion, both low and high IGF-1 appear to be risk factors for increased cancer and cardiovascular disease incidence and mortality." (PMID 33261185, 2020). "There is also an increased association with red meat and diabetes, cancer, and ischemic heart disease, whereas reduction in protein intake reduces circulating IGF-1 levels." (PMID 33287232, 2020). "We showed previously that MMP11 functions in the regulation of whole-body metabolism through activation of the IGF1/AKT/FoxO1 signaling cascade in a non-cancer context using gain- and loss-of-function genetic-engineered mice models." (PMID 32825455, 2020). "Mitogenic and anti-apoptotic activity of mature IGF1, as well as different precursor IGF1 peptides, qualify IGF1 to the group of growth factors implicated in the initiation and progression of various cancers." (PMID 32977489, 2020). "In fact, evidence suggests that cancer prognosis is affected by insulin and IGF-1 circulating levels, independently of cancer risk." (PMID 32351453, 2020). "We used 416 single‐nucleotide polymorphisms robustly associated with serum IGF‐1 levels to assess the potential causal associations between this hormone and site‐specific cancers through Mendelian randomization." (PMID 32717139, 2020). "The proliferative and antiapoptotic activities of IGF1 led to several observational studies that were aimed at elucidating the potential connection between circulating IGF1 levels and increased risk of cancer." (PMID 33182502, 2020). "A limitation is that the genetic associations with IGF‐1 levels were estimated in UK Biobank from which we also obtained genetic association estimates for cancer." (PMID 32717139, 2020). "We used the MR technique to examine the potential causal associations between serum IGF‐1 levels and site‐specific cancers." (PMID 32717139, 2020). "Relative to the unhealthy score, the healthy one scored more negatively foods rich in refined carbohydrates, which are supposed to be implicated in cancer risk through energy metabolism, insulin, and insulin-like growth factor (IGF-1) upregulations." (PMID 32640737, 2020). "These available propositions are based mostly on the results of studies on the expression of different IGF1 variants, as well as the influence of recombined analogues or synthetic IGF1 isoform products on cultured cancer cells." (PMID 32977489, 2020). "The IGF1/insulin pathway regulates growth in normal tissues and is associated with cancer development and reduced cancer survival rates." (PMID 33260481, 2020). "The associations of genetically predicted IGF‐1 levels with cancers of the colorectum, prostate, and breast were similar after adjustment for height through multivariable MR analysis." (PMID 32717139, 2020). "Bioinformatic analysis performed on almost a thousand LC patients shows that overexpression of IGF1 correlates with high risk of cancer progression." (PMID 32977489, 2020). "Insulin-like growth factor 1 (IGF1) is a key regulator of tissue growth and development that is also implicated in the initiation and progression of various cancers." (PMID 32977489, 2020). "Both GH and IGF-1 are implicated in cancer promotion through in vitro proliferative effects, with angiogenic and antiapoptotic effects." (PMID 33292786, 2020). "Real and potential prognostic-diagnostic importance of IGF1 isoforms (mRNA, protein) in selected human cancers is already described." (PMID 32977489, 2020). "On the other hand, the role of IGF-1 in stimulating tumor progression is well established, as numerous studies have shown that elevated, and even basal IGF-1 levels are strongly associated with detrimental cancer prognosis and therapy resistance." (PMID 33291663, 2020).